IL1B (interleukin 1 beta)
Diseases named in the same sentence as IL1B in open-access papers (continued):
Sharing a sentence is not in itself a finding about the gene and the disease.
Anxiety (continued). "Cytokines IL-1β and IL-18 promote neuronal hyperreactivity in the basolateral and central amygdala, enhancing fear and anticipatory anxiety responses and hindering the extinction of fear memory." (PMID 41008651, 2025). "Genetic models of T2D, such as the db/db mice, also showed anxiety-like behavior, increased levels of inflammatory cytokines (IL-1β, TNF-α, and IL-6), and reduced levels of BDNF in the hippocampus." (PMID 38279738, 2024). "Analysis of the behavior of IL-1β-exposed animals at P39 in the elevated plus-maze and open field previously showed an increase in anxiety-like behavior, indicated by significantly less time spent exploring the center zone." (PMID 36335540, 2023). "It not only increased the concentrations of cytokines, including IL-1β and IL-18, in the PFC and HC, but also caused anxiety- and depressive-like behaviors." (PMID 36747075, 2023). "Due to the link between anxiety and inflammation, expression of IL-1β, TNFα, and IFNγ genes was measured in the ileum and colon." (PMID 37960288, 2023). "Increased IL-6 levels activate the bone marrow-derived peripheral monocytes and promote their recruitment to neurovascular endothelial cells, thereby releasing IL-1β and triggering anxiety." (PMID 37273529, 2023). "In accordance with previous data, IL-1β-exposed animals spent significantly less time in the center stage of the arena, suggesting anxiety-like behavior." (PMID 36335540, 2023). "TNF-α and IL-1β have been previously shown to induce anxiety-like behavior during the EPM test in rodents." (PMID 37432552, 2023). "Central and peripheral IL-1β reduces neurogenesis and increases anxiety, stress, and abnormal social interaction." (PMID 38026692, 2023). "Further analysis revealed a positive correlation between the reduction of NLRP3/IL-1β mRNA and amelioration in anxiety in the OFT and EPM tests." (PMID 37047351, 2023). "Colocalization of interleukin-1β (IL-1β) with β2-adrenergic receptors (β2-ARs) underlies the possible influence of noradrenergic neurotransmission to increased IL-1β expression in comorbidity between social deficits and elevated anxiety comorbidity." (PMID 37284463, 2023). "Consistent with this interpretation, excessive IL-1β production in Dm was positively correlated with thigmotactic behavior, providing further evidence about the implication of this region in regulating anxiety responses." (PMID 37284463, 2023). "In Cluster 2 networks, which show more severe anxiety/somatization, sleep disruption, and body weight issues, IL-1β takes on a prominent role." (PMID 37692303, 2023). "IL-1β is essential in the pathogenesis and pathophysiology of anxiety- and depressive-like behavior." (PMID 37009013, 2023). "The outcomes showed considerable anxiety and depressive status, with an evident increase in cortisol and IL-1β titers and an important decrease in oxidative enzymes and testosterone." (PMID 36986501, 2023). "The deficiency of SCFAs exaggerates neuroinflammation by increasing IL-1β and IL-6 expression in the hippocampus, thereby promoting anxiety through inhibiting BDNF-GABA signal pathway." (PMID 37273529, 2023). "This is consistent with findings that indicated IL-6 and IL1B levels were elevated in depressive-like behavior and anxiety." (PMID 37623226, 2023). "Some of these cytokines performed fundamental functions in CNS: IL-1β in learning and synapse formation, IL-4 in neurogenesis and spatial learning, IL-17A in synaptic plasticity and in the management of anxiety." (PMID 37588589, 2023). "Behavioral tests and biochemical analyses indicated that diabetic rats showed significantly increased anxiety and depressive-like behavioral deficits, brain oxidative stress and pro-inflammatory cytokines levels (IL-1β, IL-6 and TNF-α)." (PMID 35408607, 2022). "In this study, we examined anxiety-like behavior and demonstrated that this was mediated by the proinflammatory cytokine IL-1β." (PMID 35379260, 2022).
Anxiety (continued). "Increased levels of the proinflammatory cytokine IL-1β in the brain induces a number of behavioral changes, including anxiety-like behaviors, and inhibition of IL-1β-mediated effects in the brain attenuates these behavioral changes." (PMID 35379260, 2022). "Residential microglias secrete more IL-1β and bind to IL-1R1 in the vascular endothelium to mediate anxiety-like behaviors." (PMID 36051441, 2022). "Breese’s research confirmed that IL-1β and TNF-α are involved in the sensitized anxiety response caused by repeated alcohol withdrawal." (PMID 36539796, 2022). "For example, chronic unpredictable stress induces both anxiety-like and depressive-like behaviors while increasing the expression of amygdala inflammatory cytokines, including IL-1β, IL-6, and TNF-α." (PMID 36232376, 2022). "A previous study reported that anxiety-like behavior in obese mice was associated with increased levels of TNF-α, IL-1β, and IL-6 in the brain." (PMID 35209199, 2022). "In a predator scent-stress mouse model, activation of the nuclear factor k light-chain enhancer pathway of activated B cells (NF-κB) promoted anxiety, and inhibition of this pathway reduced both IL-1β concentrations and anxiety levels." (PMID 35625690, 2022). "Cytokine production, particularly IL-1β and IL-6 production, by these cells contributes to anxiety-like behavior during social stress." (PMID 35216112, 2022). "A previous study demonstrated that knock-down of the IL-1β gene by lentivirus can inhibit LPS-induced anxiety and depressive-like behavior." (PMID 35335195, 2022). "Nevertheless, by attenuating the development of anxiety-like behaviors in colitic mice by blocking IL-1β centrally we link our observations, albeit indirectly." (PMID 35379260, 2022). "We evaluated the association of putative functional and tag SNPs within IL1B, IL2, and IL6 with aggression case status, parent‐reported internalizing problems, self‐reported anxiety symptoms, and self‐reported depressive symptoms in our sample." (PMID 36168941, 2022). "IL-1β has been confirmed to be a critical factor in neuroinflammation-induced anxiety-like behavior." (PMID 36051441, 2022). "In this recent study, an increase in the concentration of pro-inflammatory cytokines (TNF-α and IL-1β), inhibition of antioxidants enzymes (CAT, SOD) and GSH were associated with anxiety-like behaviour in diabetic rats treated with HAART." (PMID 35769902, 2022). "Direct microinjection of IL-1β or TNF-α into several brain regions induces anxiety-, depressive-like behavior, and cognitive dysfunction." (PMID 36051441, 2022). "Our studies support the principle that increased sensitivity to IL-1β production is an additional shared pathophysiological pathway in both stress model systems, which is in part responsible for their anxiety phenotypes." (PMID 33446652, 2021). "The results of these chronic sleep deprivation studies show a critical role of NLRP3 inflammasome signaling and IL-1β production in mouse hippocampus and cortex for the generation of anxiety." (PMID 33446652, 2021). "Next, we focused on molecules that are involved in the production of IL1β in two brain areas which always figure prominently in the literature related to stress and anxiety—hippocampus and amygdala." (PMID 34895246, 2021). "As deletion of Bmal1 resulted in anxiety phenotypes, we examined the production of IL-1β and expression of inflammatory genes in the hippocampus of both WT and Bmal1-/- mice." (PMID 33446652, 2021). "The cellular and molecular substrates IL-1β interacts with to generate anxiety needs to be validated." (PMID 33446652, 2021). "Inhibition of NLRP3 with a small molecule inhibitor MCC950 significantly reduced stress-induced anxiety in mice and IL1β as well as Caspase 1 activity." (PMID 34895246, 2021). "Ibrutinib-treated mice show marked reduction in stress-induced anxiety, IL1β levels and Caspase 1 activity in the hippocampus and amygdala." (PMID 34895246, 2021).
Anxiety (continued). "Partial improvement in the locomotor activity and anxiety-like behaviors by The upregulation of IL-1β and IL-6 in the hippocampus region with the restoration of surgery-induced microglial over-activation." (PMID 34497516, 2021). "For example, the production of IL-1β by monocytes adherent to the cerebral vasculature is responsible for driving anxiety behaviour in response to social stress in mice." (PMID 32213184, 2020). "Meanwhile, the central administration of IL-1β can induce anxiety-like behavior and enhance fear memory after stress encounters." (PMID 32635937, 2020). "The secondary outcome was to evaluate the possible beneficial effect of a new probiotic formulation on anxiety and related symptoms according to the IL-1β SNP rs16944." (PMID 32377159, 2020). "In this study, the primary objective was to investigate the effects of the SNP rs16944 within the IL-1β gene on anxiety development in a sample of the Italian population." (PMID 32377159, 2020). "IL-1β is an important mediator of stress-induced anxiety-like behavior and it has been reported that the hippocampal IL-1β mRNA was upregulated in stressed rats." (PMID 32265706, 2020). "Despite the numerous studies, the mechanism that links systemic inflammation and neurological disorders is still poorly understood, and nowadays, there is a gap in the scientific literature about the role of IL-1β in human anxiety." (PMID 32377159, 2020). "In this context, several reports have shown increased levels of cytokines, such as interleukin-1β (IL-1β) and interleukin-6 (IL-6) in experimental models of anxiety-depression." (PMID 31578381, 2019). "This study highlighted that microglial activation is very likely to play a role in CMS-induced depressive- and anxiety-like behavior via NLRP3 inflammasome-IL-1β signaling." (PMID 29343269, 2018). "In contrast, obese patients diagnosed with anxiety or mood disorders only showed significantly lower expression levels of IL1B in VAT and ADIPOQ in SAT when compared with obese subjects without mental disorders." (PMID 30504920, 2018). "Immunoactivation in mice and healthy volunteers by injection of lipopolysaccharide has been reported to increase circulating proinflammatory cytokine levels (IL-1β, IL-6) as well as producing symptoms of anxiety and reduced cognitive performance." (PMID 27476619, 2017). "The present study shows that stress accumulation causes an increase in extracellular ATP, the assembly of NLRP3 inflammasome, the cleavage of caspase-1, mature of IL-1β in the hippocampus as well as the depressive-like and anxiety-like behaviors in rodents." (PMID 28486969, 2017). "To investigate the role of IL-1β in EAE-induced anxiety, we chronically inhibited IL-1β signaling in these mice by icv delivery of IL-1ra." (PMID 27589957, 2016). "Here we show that BGOS supplementation in mice attenuated post-inflammation anxiety after a single injection of LPS, compared to controls, as well as diminishing the LPS-mediated elevation of IL1-β and 5-HT2ARs in the frontal cortex." (PMID 26476141, 2016). "The present investigation links the anxiety-like behavior of presymptomatic EAE mice to IL-1β-induced CB1R dysfunction on GABA synapses." (PMID 27589957, 2016). "Pro-inflammatory cytokines, including interleukin (IL)-1β and tumor necrosis factor (TNF)α, have been associated with increased anxiety, altered cognitive function, and are elevated in ASD patients." (PMID 25212412, 2014). "Results indicated that intranasal dantrolene nanoparticle treatment robustly inhibited LPS-induced increases in depressive and anxiety behavior, LPS-induced pathological elevation of IL-1β and IL-18 levels in the blood and brain, and LPS-induced activation of pyroptosis." (PMID 41633971, 2026). "In addition, the pro-inflammatory cytokines TNF-α and IL-1β have been reported to induce anxiety-like behaviors." (PMID 40906736, 2025).
Anxiety (continued). "Administration of EPA could reduce anxiety behavior in rats, as well as the stimulation of corticosterone by interleukin-1 beta." (PMID 38890670, 2024). "Moreover, pro-inflammatory cytokines (TNF-α and IL-1β), which are linked to microglia and can activate microglia, and the ACC are associated with anxiety." (PMID 39337650, 2024). "One candidate gene study found an association between pro‐inflammatory cytokine (IL‐1β) genetic variation and anxiety in both PwMS and in healthy controls, highlighting a role for immune factors in the development of anxiety, but this was not specific to MS." (PMID 38715244, 2024). "Moreover, administration of IL-10 into rats attenuated the pro-inflammatory cytokine IL-1β-induced anxiety-like symptoms in male rats, demonstrating that IL-10 possesses anxiolytic activities." (PMID 38902708, 2024). "The enhanced expression of IL-1β may alter synaptic plasticity in these brain regions, contributing to social impairments and anxiety-like behavior, observed in MK-801-treated fish." (PMID 37284463, 2023). "In addition, network analysis showed that IL-1β was the core inflammatory factor in the population of patients with more severe anxiety/somatization, sleep disruption and body weight." (PMID 37692303, 2023). "We found that IL‐1β, IL‐6, and zo‐1 mRNA levels in the hippocampus positively correlated with anxiety‐like behavior, while ocln and cldn‐8 mRNA levels negatively correlated with anxiety‐like behavior." (PMID 36650644, 2023). "The intraperitoneal administration of IL-1β induced anxiety-like behavior in mice." (PMID 36982563, 2023). "Alteration of the periphery immune system could affect CNS immune system and induce anxiety‐like behavior, therefore we further measured the levels of IL‐1β, TNF‐α, and IL‐10 in the hippocampus." (PMID 37157948, 2023). "Similarly, we demonstrated, here, that LP-211 treatment reduces astrocyte and microglial reactivity induced by IL-1β-exposure, preventing the deficit in myelination, and reducing anxiety-like behavior." (PMID 36335540, 2023). "Central administration of CpdA to adult mice blunted LPS-induced hypolocomotion and anxiety-like behavior and reduced TNF-α, IL-1β and IBA-1 (microglia marker) mRNA in the NAc, a brain region modulating anxiety and motivation and implicated in neuroinflammation-induced mood deficits." (PMID 38111048, 2023). "Thus, chronic high-fat diet consumption promoted anxiety behavior together with an increased level of the inflammatory cytokines IL-1β, IL-6, and TNF-α in the hippocampus." (PMID 37373230, 2023). "An Italian study reported the role of the IL-1β gene in developing anxiety and the effects of psychobiotics in reducing anxiety symptoms, with 43.24% of anxious subjects being A allele carriers of the IL-1β gene and the rest 11.43% of subjects being anxious non-carriers." (PMID 37448433, 2023). "However, in stress-induced animal models of anxiety, this molecule has been shown to be reduced by IL-1B and IL-2R and their downstream signaling pathways, including NF-κB." (PMID 35194013, 2022). "Notably, the correlations of TNF‐α and IL‐1β with anxiety seemed to be stronger than IL‐6 and IL‐17." (PMID 34697903, 2022). "Finally, to determine the functional significance of the elevated levels of IL-1β, we assessed anxiety-like behavior using the elevated plus maze." (PMID 35379260, 2022). "In contrast, treatment with TNF-α and IL-1β inhibitors could suppress the development of anxiety in mouse models." (PMID 35209199, 2022). "Our findings that social isolation increased IL-1β and microglia activation in the amygdala confirmed this brain region might play a potential role in driving anxiety behavioral responses of isolated mice." (PMID 36051441, 2022). "In addition, TNF-α, IL-1β, and IL-17 were positively associated with HADS-A score, while only high TNF-α was associated with anxiety occurrence." (PMID 35239774, 2022).
Anxiety (continued). "Furthermore, intracerebroventricular administration of IL‐1β increases anxiety‐like behaviours and leads to spatial memory deficits (Song, Horrobin & Leonard, 2006)." (PMID 31421056, 2021). "IL-1β administration was reported to increase anxiety in WT mice; thus, we hypothesized that Il1b KO might rescue the behavioral abnormalities observed in Ehmt1Δ/+ mice." (PMID 34258564, 2021). "Thus, the ability of FDP to reduce brain IL-1β in response to chronic sleep deprivation and the role of IL-1R in generating anxiety support anxiolytic properties of FDP." (PMID 33446652, 2021). "Furthermore, IL-1β carriers have moderate risk to develop anxiety (OR = 5.90), and in POSG IL-1β carriers, we observed a reduction of HAM-A score (p = 0.02)." (PMID 32377159, 2020). "However, QUER has shown the potential to improve abnormalities, such as anxiety-like behaviors, and neuroinflammation by continuously reducing the levels of IL-6 and IL-1β induced by LPS." (PMID 32419805, 2020). "Other recent studies report that diets high in sugars, processed foods (i.e., meat products), and/or fats are related with higher anxiety levels through alterations of glucose, protein and energy homeostasis, and increases in inflammatory cytokines (i.e., IL-6, IL-1β, TNFα) and corticosterone." (PMID 31159322, 2019). "Thus, IL-1β and adiponectin mRNA levels were significantly lower in obese patients with anxiety/mood disorders (A/MD subgroup) than in obese patients without mental disorders (non-MD subgroup)." (PMID 30504920, 2018). "Linear regression analysis was used to determine whether the temporal variation across AE of the anger and anxiety state score could be explained by the temporal variation of IL-1β and IL-6 levels in plasma and saliva ascertained at the same time." (PMID 29445205, 2018). "We have previously reported that the downregulation of CB1R-mediated control of GABA synapses in the striatum represents a reliable synaptic correlate of anxiety induced by chronic psychoemotional stress or by a single intracerebroventricular injection of IL-1β." (PMID 27589957, 2016). "Notably, HSP resulted in a significant attenuation of anxiety- and depression-associated behaviors, a reduction in pro-inflammatory cytokine levels (TNF-α, IFN-γ, IL-1β, IL-2, IL-6), and an augmentation of neurotrophic factors (NT-3, BDNF, NGF) within the striatum." (PMID 41346684, 2025). "Finally, il1β expression in the CA1 was negatively correlated with time spent in the center in the OFT (r = −0.343, p = 0.03), suggesting that lower il1β levels were associated with increased time spent in the center (i.e., less anxiety-like behavior)." (PMID 40558565, 2025). "IL-1β is involved in stress-induced neuroinflammation, which may lead to anxiety-like behavior." (PMID 39941015, 2025). "Activated caspase-1 cleaves Pro-IL-1β and Pro-IL-18 into their active forms, IL-1β and IL-18, thereby stimulating hippocampal inflammatory cells, exacerbating inflammation, promoting the formation of neurotoxic A1 astrocytes, and inducing depressive-like behaviors such as anxiety and despair." (PMID 39114351, 2024). "Previous studies have linked Romboutsia and Turicibacter to circulating inflammation (IL-1β) and behavioral outcomes (hypersomnia and anxiety-like behavior), indicating that an increase in Romboutsia and Turicibacter exacerbates inflammation and anxiety-like behavior." (PMID 38595919, 2024). "Oxidative stress, high levels of cytokines (TNF-α, IL-1β, IL-6, IL-10), and dysregulation of the proliferation and differentiation of oligodendrocytes and astrocytes were observed in the prefrontal cortex and hippocampus of T1D mice exhibiting concomitantly anxiety-like behavior." (PMID 38279738, 2024).